MIR4504 (microRNA 4504)
Synonyms: hsa-mir-4504
Gene: MicroRNA gene on chromosome 14 (50,299,855 to 50,299,946, reverse strand). Ensembl gene ENSG00000264712.
Homologues: Orthologues: chimpanzee MIR4504 (100% identical).